SMG1 (SMG1 nonsense mediated mRNA decay associated PI3K related kinase)
Description:
Serine/threonine protein kinase involved in both mRNA surveillance and genotoxic stress response pathways. Recognizes the substrate consensus sequence [ST]-Q. Plays a central role in nonsense-mediated decay (NMD) of mRNAs containing premature stop codons by phosphorylating UPF1/RENT1. Recruited by release factors to stalled ribosomes together with SMG8 and SMG9 (forming the SMG1C protein kinase complex), and UPF1 to form the transient SURF (SMG1-UPF1-eRF1-eRF3) complex. In EJC-dependent NMD, the SURF complex associates with the exon junction complex (EJC) through UPF2 and allows the formation of an UPF1-UPF2-UPF3 surveillance complex which is believed to activate NMD. Also acts as a genotoxic stress-activated protein kinase that displays some functional overlap with ATM. Its depletion leads to spontaneous DNA damage and increased sensitivity to ionizing radiation (IR). May activate PRKCI but not PRKCZ.
Synonyms: ATX; KIAA0421; LIP; 61E3.4
Tractability: Small molecule: a structure with a bound ligand is known; a high-quality ligand is known; it belongs to a druggable protein family. PROTAC: ubiquitination databases record sites on it; its protein half-life has been measured; a small molecule that binds it is known.
Target class: Kinase; Enzyme; Protein Kinase
Chemical probes: SMG1i (high quality)
Gene: Protein-coding gene on chromosome 16 (18,804,860 to 18,926,412, reverse strand). Ensembl gene ENSG00000157106.
Subcellular location: Nucleus; Cytoplasm
Subcellular location (Human Protein Atlas): Nucleoplasm; Cell Junctions; Plasma membrane; Primary cilium; Vesicles
Pathways (Reactome):
Metabolism of RNA: Nonsense Mediated Decay (NMD) enhanced by the Exon Junction Complex (EJC)
Gene Ontology:
Molecular function: protein binding; protein serine/threonine kinase activity; RNA binding; telomeric DNA binding; protein kinase activity; kinase activity; protein serine kinase activity
Biological process: DNA damage response; nuclear-transcribed mRNA catabolic process, nonsense-mediated decay; peptidyl-serine phosphorylation; phosphatidylinositol phosphate biosynthetic process; protein autophosphorylation; regulation of telomere maintenance; mRNA export from nucleus; regulation of nuclear-transcribed mRNA catabolic process, nonsense-mediated decay
Cellular component: cytoplasm; nucleoplasm; nucleus; serine/threonine protein kinase complex; chromatoid body; cytosol
Genetic constraint (gnomAD): Loss-of-function variants: 21 observed, 301.54 expected, observed/expected ratio (o/e) 0.0696, 90% interval 0.048 to 0.1. The upper end of that interval is the gene's LOEUF score, 0.1, which puts it in group 1 of 6, group 1 being the genes least tolerant of losing a copy. Missense variants: 2,640 observed, 3,375.6 expected, observed/expected ratio (o/e) 0.78, 90% interval 0.76 to 0.81. Synonymous variants: 1,294 observed, 1,202 expected, observed/expected ratio (o/e) 1.08, 90% interval 1.03 to 1.13.
Homologues: Orthologues: macaque SMG1 (99% identical), pig SMG1 (99% identical), chimpanzee SMG1 (98% identical), mouse Smg1 (98% identical), rabbit SMG1 (98% identical), rat Smg1 (98% identical), guinea pig SMG1 (97% identical), tropical clawed frog smg1 (86% identical), zebrafish smg1 (73% identical), Drosophila melanogaster nonC (23% identical), Caenorhabditis elegans smg-1 (16% identical). Paralogues in human: PRKDC (12% identical), ATM (11% identical), ATR (9% identical), MTOR (9% identical), TRRAP (8% identical).
Diseases named in the same sentence as SMG1 in open-access papers:
SMG1 is named in the same sentence as 55 diseases in open-access papers, as found by Europe PMC text mining. Sharing a sentence is not in itself a finding about the gene and the disease. The quoted sentences say what the papers report.
hepatocellular carcinoma (10 papers, 2019 to 2024). A malignant tumor that arises from hepatocytes. "Lately, estrogen receptor α (ERα), a protein associated with progression of hepatocellular carcinoma (HCC), was found to directly bind to the 5′ promoter region of its host gene SMG1, thereby suppressing the circular RNA-SMG1.72 expression." (PMID 34335937, 2021). "Knockdown of SMG1 in HepG2, a hepatocellular carcinoma cell line, resulted in similar increases in MVA pathway genes and in ABCA1, though to a lesser extent." (PMID 35805027, 2022). "SMG1 was reported to play a tumor-suppressive function in tumors, like acute myeloid leukemia, gastric carcinogenesis, hepatocellular carcinoma and nasopharyngeal carcinoma." (PMID 34784955, 2021). "MAGI2-AS3 also regulates proliferation and metastasis of hepatocellular carcinoma cells through the mir-374b-5p/SMG1 axis." (PMID 33231563, 2020). "Moreover, MAGI2-AS3 hampers hepatocellular carcinoma cell growth and its invasion through sponging miR-374b-5p to up-regulate SMG1 axis." (PMID 32727450, 2020). "In hepatocellular carcinoma, MAGI2-AS3 targets miR-374b-5p/SMG1 to inhibit proliferation and migration of HCC cells." (PMID 32138716, 2020). "The upregulation or overexpression of SMG-1 potentially suppresses tumor growth and metastasis, whereas SMG-1 downregulation promotes tumor progression in gastric cancer and hepatocellular carcinoma." (PMID 39506517, 2024). "Additionally, decreased SMG1 expression has been shown in acute myeloid leukemia (AML), colorectal cancer, hepatocellular carcinoma and HPV-positive head and neck squamous cell carcinoma cells." (PMID 31659158, 2019). "However, miR-192 serves as a poor prognosis marker in other cancer types including neuroblastoma targeting Dicer1, gastric cancer targeting RAB11-FIP2 and SMG-1, NSCLC targeting the FGFR3/RB1 pathway, hepatocellular carcinoma targeting SEMA3A, and pancreatic cancer targeting SIP1." (PMID 33614788, 2021).
gastric cancer (8 papers, 2016 to 2024). A primary or metastatic malignant neoplasm involving the stomach. "miR-192 enhances epithelial-mesenchymal transition of gastric cancer by inhibiting SMG-1 and inactivating Wnt signaling pathway." (PMID 33097010, 2020). "The significant expression changes of MIR7 (p-value < 0.151) and SMG1 (p-value < 0.009) between normal gastric cells and gastric cancer cells also supported the result that MIR7 and SMG1 play important role in Human gastric carcinogenesis." (PMID 26897165, 2016). "It has been reported that both MIR7 and SMG1 are involved in the initiation and progression of inflammation-induced gastric cancer." (PMID 26897165, 2016).
pancreatic cancer (6 papers, 2019 to 2024). "SMG1, a member of the phosphoinositide kinase‐like kinase family, plays a role in several diseases progression, including pancreatic cancer, Physcomitrella patens and inflammation‐enhanced cancer." (PMID 32827242, 2020). "However, contradictory findings have also been reported by other studies, suggesting diverse roles of SMG-1 in cancer.SMG-1 knockdown inhibited pancreatic cancer cell proliferation and increased chemosensitivity." (PMID 39506517, 2024). "We study the effect of SMG1 expression (main kinase that initiates NMD) in the survival and the nature of the tumor immune infiltration using TCGA RNAseq and scRNAseq datasets of breast, lung and pancreatic cancer." (PMID 36443756, 2022).
acute myeloid leukemia (5 papers, 2014 to 2023). Acute myeloid leukemia (AML) is a group of neoplasms arising from precursor cells committed to the myeloid cell-line differentiation. "To investigate the function of SMG1 in acute myeloid leukemia (AML), we performed methylation-specific polymerase chain reaction and found that SMG1 was hypermethylated in the promoter region." (PMID 25257528, 2014). "Furthermore, SMG1 inhibitors might be effective in other malignancies that depend on the UPR for survival such as Waldenström's macroglobulinemia, acute myeloid leukemia (AML), as well as other solid tumor types." (PMID 36400430, 2023).
breast carcinoma (5 papers, 2012 to 2024). "We next correlated the expression of commonly shared identified genes; BIRC6, MAP3K2, USP4 and SMG1 with immune populations in different breast cancer subtypes." (PMID 38710724, 2024). "Only 0.5% of the total transcriptome correlated with the presence of Tregs and only four transcripts, BIRC6, MAP3K2, USP4 and SMG1, were commonly shared among the different breast cancer subtypes." (PMID 38710724, 2024). "As SMG1 is the first factor to initiate NMD activation and showed a high-predicted value of tumor survival and inflammation we generated SMG1KD-derived cells from 4T1 breast cancer, Panc02 for Pancreatic Adenocarcinoma and B16/F10 as Melanoma murine models." (PMID 36443756, 2022).
head and neck squamous cell carcinoma (5 papers, 2014 to 2024). A squamous cell carcinoma that arises from any of the following anatomic sites: lip and oral cavity, nasal cavity, paranasal sinuses, pharynx, larynx, and salivary glands. "In accordance with our study, SMG1 was down-regulated due to its promoter hypermethylation and its over-expression protected HPV-positive cells from radiation in head and neck squamous cell carcinoma." (PMID 25257528, 2014). "Recently, SMG1 was suggested to be a potential tumor suppressor and could be down-regulated due to promoter hypermethylation in human papillomavirus (HPV)-positive head and neck squamous cell carcinoma." (PMID 25257528, 2014).
lung carcinoma (5 papers, 2012 to 2022). "In mice, total loss of SMG1 is embryonic lethal and loss of a single allele results in an increased rate of cancer development, particularly haematopoietic cancers and lung cancer." (PMID 31565865, 2019). "The decreased MARVELD1 level in lung cancer reduces NMD efficiency through diminishing the association between NMD complex component UPF1/SMG1 and premature termination codons containing mRNA (PTC-mRNA)." (PMID 25520033, 2014). "We further detected the potential interaction between endogenous MARVELD1 and SMG1 in lung cancer cell line NCI-H292 by using Co-IP followed by western blotting analysis." (PMID 25520033, 2014). "In this study, we showed MARVELD1 co-localized and interacted with SMG1, the core kinase of the NMD machinery, in lung cancer cells." (PMID 25520033, 2014). "To validate this hypothesis, we analyzed the expression of SMG1 and STAT3 factors by qRT-PCR in a repertoire of human tumor cell lines (29 in total, of different origins, including many lung cancer cell lines), that were selected for their positiveness for IL-6 production." (PMID 36443756, 2022). "Moreover, we constructed the NMD reporter plasmid expressing PTC-containing truncated LRP1B-GFP mRNA (LRP1B exons 1–9 from lung cancer cell line QG56), and demonstrated that MARVELD1 bound PTC-mRNA as efficient as NMD core factor UPF1 and SMG1 by RNA-ChIP based reporter system." (PMID 25520033, 2014).
bladder cancer (3 papers, 2021 to 2022). "CircRNA_0000326 promotes the progression of bladder cancer through miR338-3p to regulate proto-oncogenes, while circRNA CircPPP1CB suppresses bladder cancer tumorigenesis via the miR-1307-3p/SMG1 axis." (PMID 35453537, 2022). "Another study indicates that circPPP1CB inhibits human bladder cancer growth, metastasis, and EMT process by modulating the miR-1307-3p/SMG1 axis." (PMID 35864511, 2022).
COVID-19 (3 papers, 2022 to 2024). A disease caused by infection with severe acute respiratory syndrome coronavirus 2. "The mRNA gene SMG1 showed two different signs (+, −) in two formulas and did not appear in the third formula presented in Section 3, which suggests that we need three different types (both mRNA and non-mRNA) of vaccines to cover the entire possible spectrum of COVID-19 variants." (PMID 35632517, 2022). "Taking the SMG1 gene as an example, an increase (or a decrease) of SMG1 expression levels that are good for one signature pattern of COVID-19 will be bad for another signature pattern." (PMID 35632517, 2022). "As a result, it is safe to conclude that the five genes, ABCB6, KIAA1614, MND1, RIPK3, and SMG1, are truly COVID-19 specific, and the newly proposed classification method is a powerful tool." (PMID 35632517, 2022).
melanoma (3 papers, 2012 to 2022). A malignant, usually aggressive tumor composed of atypical, neoplastic melanocytes. "Even though melanoma was not one of the top tumor types that crosslink survival and SMG1 expression in TCGA, we chose to include this model as well to evaluate whether future pharmacological NMD inhibition could be translated onto a broader range of tumors." (PMID 36443756, 2022).
nasopharyngeal carcinoma (3 papers, 2019 to 2022). A carcinoma arising from the nasopharyngeal epithelium. "MiR-18a exerted its oncogenic effects by inhibiting SMG1 and activating the mTOR pathway in nasopharyngeal carcinoma (NPC) cells." (PMID 35223996, 2022).
ovarian carcinoma (3 papers, 2021 to 2025). A malignant neoplasm originating from the surface ovarian epithelium. "SMG1 expression was discovered to be significantly reduced in ovarian cancer tissues and cells, and its expression in ovarian cancer tissues was negatively associated with miR-320a level." (PMID 34784955, 2021). "Another study reported that curcumin inhibited cell proliferation and increased apoptosis in ovarian cancer by regulating the circ-PLEKHM3/miR-320a/SMG1 axis." (PMID 41010991, 2025). "Here, we found that curcumin inhibited ovarian cancer cell proliferation and promoted apoptosis, and first confirmed it was associated with the regulatory network of circ-PLEKHM3/miR-320a/SMG1." (PMID 34784955, 2021). "More importantly, SMG1 had been found to repress ovarian cancer cell proliferation, migration and invasion." (PMID 34784955, 2021). "SMG1 was targeted by miR-320a, and its knockdown also reversed the regulation of miR-320a inhibitor on the proliferation and apoptosis of ovarian cancer cells." (PMID 34784955, 2021). "Curcumin restrained proliferation and facilitated apoptosis in ovarian cancer by regulating the circ-PLEKHM3/miR-320a/SMG1 axis." (PMID 34784955, 2021). "To explore whether SMG1 could be regulated via circ-PLEKHM3/miR-320a axis in ovarian cancer cells, we measured SMG1 expression in SKOV3 and A2780 cells co-transfected with oe-circ-PLEKHM3 and miR-320a mimic." (PMID 34784955, 2021). "In conclusion, curcumin could suppress proliferation and promote apoptosis in ovarian cancer, possibly via regulating circ-PLEKHM3/miR-320a/SMG1 axis." (PMID 34784955, 2021). "However, it is not clear whether curcumin mediates ovarian cancer progression by regulating the circ-PLEKHM3/miR-320a/SMG1 axis." (PMID 34784955, 2021).
Sepsis (3 papers, 2020 to 2022). Sepsis is defined as life-threatening organ dysfunction caused by a dysregulated host response to infection. "In summary, we found circVMA21 alleviated sepsis‐associated AKI via regulating miR‐9‐3p/SMG1/inflammation and oxidative stress." (PMID 32827242, 2020). "In conclusion, circVMA21 plays an important role in the regulating sepsis‐associated AKI via adjusting miR‐9‐39/SMG1/inflammation axis and oxidative stress." (PMID 32827242, 2020). "As human SMG1 was highly expressed in kidney, we hypothesis SMG1 plays an important role in the sepsis‐associated acute kidney injury, which could also lead to excessive production of ROS and cell apoptosis." (PMID 32827242, 2020). "In sepsis-related studies, it was found that circRNA_MA21 can ameliorate sepsis-induced renal injury by modulating the miR-9-3p/SMG1 axis." (PMID 35264058, 2022). "For example, the highly differential model for SMG1 is sepsis, the model for SLC25a52 is secondary renal amyloidosis, and the model for Zbtb5 is non-small-cell lung cancer." (PMID 34440578, 2021).
colorectal cancer (2 papers, 2019 to 2023). A primary or metastatic malignant neoplasm that affects the colon or rectum. "Genes implicated in the NMD pathway, such as Upf1, Upf2, Smg1, Smg6, and Smg7, are expressed in higher levels in colorectal cancer (CRCs) with microsatellite stability, and promote tumor growth in xenograft models." (PMID 37888706, 2023).
glioblastoma (2 papers, 2021 to 2025). The most malignant astrocytic tumor (WHO grade IV). "This strategy is readily applicable to human glioblastoma as NMD pathway is important for gliomagenesis detection and SMG1 mRNA expression is present in glioma cells (TCGA_GBM data)." (PMID 34532286, 2021). "miR-490* constrains proliferative capacity in glioblastoma by repressing telomere-maintenance genes Telomeric Repeat-binding Factor 2 (TERF2), Tankyrase 2 (TNKS2) and Serine/Threonine-protein kinase, (SMG1), inducing telomere dysfunction and DNA-damage signalling." (PMID 41468376, 2025).
liver cancer (2 papers, 2023 to 2025). An epithelial or non-epithelial malignant neoplasm that arises from the liver. "Further analysis demonstrated that the overexpression of MAGI2-AS3 can inhibit the proliferation and migration of liver cancer cells by targeting the miR-374b-5p/SMG1 signaling pathway." (PMID 40636781, 2025). "For example, lncRNA PDPK2p/PDK1/AKT/caspase-3 signaling pathway can inhibit apoptosis, while the lncRNA MAGI2-AS3/miR-374b-5p/Smg1 axis can promote apoptosis in liver cancer cells." (PMID 37313458, 2023).
thyroid cancer (2 papers, 2022 to 2025). "The upregulation of miR-362-5p counteracted the effects of GAS5, and the overexpression of SMG1 negated the impact of miR-362-5p upregulation on iodine 131-resistant thyroid cancer cells." (PMID 40463874, 2025). "Moreover, the lncRNA GAS5 was shown to enhance radiosensitivity through miR-362-5p/SMG1 axis in thyroid cancer." (PMID 35600868, 2022).
B-cell lymphomas (1 paper, 2023). "Similarly, transfecting B-cell lymphomas with a CD40-agonist aptamer SMG1-shRNA chimera inhibited NMD activity, due to SMG1 kinase knockdown, and improved survival of mice with B-cell lymphomas." (PMID 36979701, 2023).
colon cancer (1 paper, 2022). "To confirm SMG1 silencing induced by the AS1411-SMG1 AsiC SMG1, we transfected it into murine colon cancer cell line CT26 or added directly on the cells for free uptake." (PMID 35991316, 2022).
colorectal adenocarcinoma (1 paper, 2024). The most common type of colorectal carcinoma. "The first was a loss-of-function inversion, deletion, and duplication in SMG1 in a colorectal adenocarcinoma sample (POG117)." (PMID 39406235, 2024).
dementia (1 paper, 2013). Loss of intellectual abilities interfering with an individual's social and occupational functions. "To test this, we performed SMG1 western analyses on posterior cingulate cortex from patients that had either PD (n = 8) or PD with dementia (PDD, n = 8) and compared SMG1 expression from these patients to healthy controls (n = 8)." (PMID 24204929, 2013). "Moreover, SMG1 protein levels were significantly reduced in brain regions with high p-syn levels in both dementia with Lewy bodies (DLB) and Parkinson’s disease with dementia (PDD)." (PMID 24204929, 2013).
dementia with Lewy body (1 paper, 2013). "To determine if reduced SMG1 expression could be specific to PD and PDD, or might be more generalizable to other synucleinopathies, we assessed SMG1 expression in temporal cortex from 6 controls and 6 dementia with Lewy body (DLB) patients." (PMID 24204929, 2013).